PRR11 (proline rich 11)
Diseases named in the same sentence as PRR11 in open-access papers (continued):
Sharing a sentence is not in itself a finding about the gene and the disease.
gastric cancer (9 papers, 2015 to 2025). A primary or metastatic malignant neoplasm involving the stomach. "Evaluation of human gastric cancer samples demonstrated that PRR11 expression was also associated with increased CTHRC1 and decreased LXN expression." (PMID 26252227, 2015). "In an effort to probe this question, the current study was conducted to characterize PRR11 expression in gastric carcinoma along with any association with clinicopathologic characteristics." (PMID 26252227, 2015). "Moreover, PRR11 has been regarded as a potential biomarker target for cancer treatment in the future, since it shows a significant association with poor prognosis in human cancers, such as gastric cancer and cholangiocarcinoma." (PMID 33276775, 2020). "Of note, two subsequent studies reported that PRR11 also has oncogenic potential and prognostic value in both gastric cancer and hilar cholangiocarcinoma, further demonstrating the critical role of PRR11 in both cell cycle progression and tumorigenesis." (PMID 28257042, 2017). "High intensity of PRR11 immunostaining was observed specifically in gastric cancer cells, and the staining intensity was variable between patients." (PMID 26252227, 2015). "In the present study, we investigated the role of PRR11 in gastric cancer by evaluating its expression status in samples from a cohort of 216 patients with gastric cancer." (PMID 26252227, 2015). "Survival analysis of the cohort revealed that PRR11 is an independent prognostic factor for gastric cancer patients." (PMID 26252227, 2015). "Our study found that both PRR11 mRNA and protein are up-regulated in GC tissues compared with normal mucosa; a finding which supports the notion of a pro-oncogenic role of PRR11 in gastric carcinoma." (PMID 26252227, 2015). "The expression of PRR11 was evaluated by immunohistochemistry in a cohort of 216 patients with gastric carcinoma." (PMID 26252227, 2015). "Additional in vitro and in vivo studies revealed that knockdown of PRR11 inhibits GC cell proliferation, colony forming ability, and tumor growth in a gastric carcinoma cell line." (PMID 26252227, 2015). "Correlation between overexpression of PRR11 and clinicopathological of gastric cancer." (PMID 26252227, 2015). "We performed Western blot analysis to explore whether the expression of CTHRC1 and LXN was altered in PRR11-KO SGC-7901 gastric cancer cells." (PMID 26252227, 2015). "In addition, we have established a gastric carcinoma cell line in which PRR11 is stably knocked down." (PMID 26252227, 2015). "Our study supports a potential prognostic role for measuring PRR11 in gastric carcinoma as Kaplan-Meier analyses demonstrated that positive expression level of PRR11 was associated with poor prognosis in both early TNM stage (TNM I/II) and in late TNM stage (TNM III/IV)." (PMID 26252227, 2015). "In addition, silencing of PRR11 in multiple gastric carcinoma cell lines inhibited cellular proliferation rates, cancer cell migration in cell colony formation, and tumor growth in vivo experiment." (PMID 26252227, 2015). "At last, the four genes, DTNA, PRR11, TMEM178B, and CACNA1D, were mainly related to gastric cancer or prostate cancer." (PMID 32964043, 2020). "However, at present, knowledge concerning the role of the PRR11 in gastric cancer has not been previously reported." (PMID 26252227, 2015).
ovarian carcinoma (8 papers, 2020 to 2025). A malignant neoplasm originating from the surface ovarian epithelium. "More significantly, in vivo xenograft tumor growth, deriving from ovarian cancer cells, is accelerated by PRR11." (PMID 36551227, 2022). "Concluding from the clinical features of 51 pairs of ovarian cancer patients and 49 primary invasive ovarian cancer patients, PRR11 is positively correlated with improved FIGO stage, larger tumor size, more lymph node metastasis and shorter overall survival." (PMID 36551227, 2022). "The expression of PRR11 is closely related to tumorigenesis, progression and poor prognosis in cancers, including lung, gastric, pancreatic, breast, esophageal and ovarian cancers." (PMID 34488538, 2021). "For example, when PRR11 was knockdown in ovarian cancer, a decrease in tumour growth was noted." (PMID 40871563, 2025). "Compared to normal ovarian surface epithelium tissues and a normal ovarian epithelial cell line IOSE80, PRR11 expression is significantly upregulated in 51 pairs of ovarian cancer tissues and 4 ovarian cancer cell lines, including Caov3, SKOV3, OVCAR3 and HO-8910." (PMID 36551227, 2022). "Hence, PRR11 serves as a reliable prognostic and diagnostic indicator in TSCC, NSCLC, BRCA, GC, HCC, HCCA, Pancreatic cancer and Ovarian cancer." (PMID 36551227, 2022). "Therefore, this study aims to evaluate the expression levels of PRR11 protein and its role in human ovarian cancer." (PMID 33276775, 2020). "And based on our report, the association between PRR11 and PCI score in ovarian cancer may require further sample size expansion for in-depth analysis." (PMID 33276775, 2020). "PRR11 is overexpressed in ovarian cancer, and has the potential to be used as a molecular marker." (PMID 32843852, 2020). "To summarize, PRR11 could be a reliable prognostic factor for ovarian cancer patients." (PMID 36551227, 2022). "Similarly, in in vivo models, PRR11 promoted xenograft tumor growth in tumor size, weight and Ki-67 expression in TSCC, NSCLC, GC, CRC, HCC and Ovarian cancer." (PMID 36551227, 2022). "As for its contribution in tumorigenicity, PRR11 facilitates cellular proliferation in vitro in BRCA, Pancreatic cancer and Osteosarcoma; likewise, it contributes to the tumorigenicity of in vitro and in vivo models in TSCC, ESCC, NSCLC, GC, CRC, HCC, HCCA and Ovarian cancer." (PMID 36551227, 2022). "We showed that the expression of PRR11 had no statistical significance during the early stages of the ovarian cancer on survival analysis data though, which may because the number of subjects is too small to yield reliable results." (PMID 33276775, 2020). "Also, a comparison between the expression of PRR11 in patients with FIGO stages III and IV, and whether the expression of PRR11 is related to PCI score in ovarian cancer patients, was conducted, whether PRR11 affects the prognosis of ovarian cancer patients by regulating the PCI score." (PMID 33276775, 2020). "Compared with non-tumorous tissues, PRR11 is evidently upregulated in tumor tissues, including ESCC, NSCLC, CRC, HCC, Pancreatic cancer, Ovarian cancer and Osteosarcoma, which would contribute to the improvement of clinical diagnosis in these cancers." (PMID 36551227, 2022).
pancreatic cancer (8 papers, 2019 to 2025). "The expression level of PRR11 in patients with pancreatic cancers was significantly higher than those of normal patients." (PMID 36551227, 2022). "Analysis of clinical parameters of 38 pancreatic cancer samples and 10 normal pancreatic tissues demonstrated that PRR11 overexpression is positively correlated with tumor invasion and differentiation, accompanied by shorter overall survival." (PMID 36551227, 2022). "As we will mention, miR-144-3p was shown to induce cell cycle arrest and apoptosis by targeting proline-rich protein 11 (PRR11) via affecting the mitogen-activated protein kinase (MAPK) signal pathway in pancreatic cancer." (PMID 33046994, 2020). "The miRNA hsa-miR-144 is closely correlated with multiple human malignant tumors, in that it induces cell cycle arrest and apoptosis in pancreatic cancer by targeting PRR11." (PMID 31428151, 2019). "USP34 facilitated pancreatic cancer cell progression targeting PRR11." (PMID 36551227, 2022). "In summary, PRR11 might be a reliable prognostic factor for pancreatic cancer patients, for which the biological interventions should be further validated." (PMID 36551227, 2022). "In vitro, PRR11 knockdown markedly inhibited cellular migration in pancreatic cancer cells." (PMID 36551227, 2022). "MiR-144-3p by targeting PRR11 could induce cell cycle arrest and apoptosis in pancreatic cancer cells via MAPK signaling pathway." (PMID 33330110, 2020). "Notably, further exploration of treating pancreatic cancers revealed that ubiquitin specific protease 34 (USP34) knockdown inhibited proliferation and migration, and induced apoptosis targeting PRR11." (PMID 36551227, 2022).
prostate carcinoma (8 papers, 2020 to 2025). A carcinoma that arises from epithelial cells of the prostate gland. "The overexpression of miR-195 has been reported to markedly suppress prostate cancer cell proliferation and tube formation by downregulating proline-rich protein 11 (PRR11) expression." (PMID 33101368, 2020). "Notably, miRNA-195-5p was also found to be downregulated in human prostate cancer and inhibit cell proliferation and angiogenesis by downregulating PRR11 expression." (PMID 32076467, 2020).
hilar cholangiocarcinoma (7 papers, 2015 to 2025). A cholangiocarcinoma that arises from the junction, or adjacent to the junction, of the right and left hepatic ducts. "Gastrointestinal tissue microarrays were used to evaluate PRR11 expression and its association with clinical outcome was analyzed in patients with hilar cholangiocarcinoma." (PMID 25971332, 2015). "A similar knock out experiment of PRR11 in hilar cholangiocarcinoma cell lines resulted in decreased cellular proliferation, migration, and tumor growth." (PMID 31277598, 2019). "Overexpression of PRR11 was observed in esophageal, gastric, pancreatic, colorectal, and hilar cholangiocarcinoma." (PMID 25971332, 2015). "During this analysis, it was observed that PRR11 expression was increased in invasive hilar cholangiocarcinoma (HC) relative to normal tissue and precursor lesions." (PMID 25971332, 2015). "A recent study reported that PRR11 signals could significantly induce the expression of EGR1 gene in patients diagnosed with hilar cholangiocarcinoma patients." (PMID 33276775, 2020). "Furthermore, the expression of EGR1 was decreased by silencing PRR11, which has oncogenic effects in hilar cholangiocarcinoma." (PMID 27835650, 2016).
non-small cell lung carcinoma (7 papers, 2020 to 2024). A group of at least three distinct histological types of lung cancer, including non-small cell squamous cell carcinoma, adenocarcinoma, and large cell carcinoma. "In non-small cell lung carcinoma, PRR11 drives F-actin assembly by recruiting the actin-related protein 2/3 complex." (PMID 38427643, 2024). "This is consistent with the previously reported role of PRR11 in non-small cell lung carcinoma." (PMID 38427643, 2024). "Additionally, PRR11 activated the Akt/mTOR autophagy signaling pathway to facilitate tumorigenesis in non-small cell lung cancer, suggesting that this gene may affect cancer cells through different signal transduction pathways." (PMID 34488538, 2021). "In non-small cell lung cancer (NSCLC) cells, cellular apoptosis and autophagy would be reduced by PRR11." (PMID 36551227, 2022).
esophageal cancer (5 papers, 2020 to 2024). A primary or metastatic malignant neoplasm involving the esophagus. "A GEO-based prognostic model consisting of six gene products (ARHGAP11A, H1.4, HMGB3, LRIG1, PRR11, and COL4A1) has been shown to be a reliable predictor of esophageal cancer." (PMID 39062899, 2024). "A prognostic model consisting of six gene products (HMGB3, ARHGAP11A, H1.4, LRIG1, PRR11, and COL4A1) is a reliable predictor of esophageal cancer." (PMID 39062899, 2024). "In esophageal cancer, the 5-year survival rate of high expression of PRR11 was significantly lower than that of the low expression group, which may be related to the interaction of PRR11 with destructive complexes (APC, GSK-3β and AXIN2) to activate the Wnt/β-catenin pathway." (PMID 34659555, 2021).
tongue squamous cell carcinoma (5 papers, 2020 to 2025). A squamous cell carcinoma that arises from the tongue. "In Tongue Squamous Cell Carcinoma (TSCC) cells, PRR11 can promote proliferation and invasion by regulating p21, p27, CDK2, and Cyclin A to facilitate S phase progression." (PMID 32180800, 2020).
glioblastoma (4 papers, 2022 to 2026). The most malignant astrocytic tumor (WHO grade IV). "In glioblastoma, PRR11 inhibits ferroptosis by stabilizing dihydroorotate dehydrogenase (DHODH), suggesting indirect links to lipid peroxidation in lipid metabolism." (PMID 41602397, 2026). "In glioblastoma, PRR11–DHODH interactions contribute to temozolomide resistance, while DHODH inhibition sensitizes tumors to ferroptosis and restores drug response." (PMID 41369379, 2025). "In glioblastoma, DHODH stabilization by PRR11 was found to maintain mitochondrial function and ferroptosis resistance, further enhancing temozolomide resistance." (PMID 41369379, 2025). "For example, DHODH is a downstream regulator of PRR11, which maintaining DHODH protein stability by inhibiting the binding between E3 ubiquitin ligase HERC4 and DHODH in glioblastoma." (PMID 40715045, 2025).
osteosarcoma (4 papers, 2021 to 2025). A usually aggressive malignant bone-forming mesenchymal neoplasm, predominantly affecting adolescents and young adults. "Relative higher expression of PRR11 was also observed in osteosarcoma cell lines, including SAOS2, MG63 and U2OS." (PMID 36551227, 2022). "Compared with paracancerous tissues, PRR11 expression is elevated in 62 cases of osteosarcoma tissues." (PMID 36551227, 2022). "In further analysis of PRR11 expression in osteosarcoma patients, high PRR11 expression is correlated with larger tumor size, advanced Enneking stage and lymph node metastasis." (PMID 36551227, 2022). "The relationship between PRR11 expression in human osteosarcoma tissues and its clinicopathological features were analysed using a χ2 test." (PMID 34659555, 2021). "The low expression of PRR11 can inhibit the proliferation, migration and invasion of osteosarcoma cells, and promote apoptosis." (PMID 34659555, 2021). "In order to further study the potential mechanism of PRR11 in osteosarcoma, we selected osteosarcoma cell lines for in vitro experiments." (PMID 34659555, 2021). "First, RT-PCR and Western blotting were used to detect the expression level of PRR11 in the osteosarcoma cell line and the human osteoblast cell line hFOB1.19." (PMID 34659555, 2021). "IHC detected the expression of PRR11 in 62 cases of osteosarcoma tissues and paracancerous tissues, and found that PRR11 was located in the cytoplasm and presented a brownish-yellow or tan distribution." (PMID 34659555, 2021). "RT-PCR was used to detect the expression of PRR11 mRNA in 62 cases of osteosarcoma tissues and paracancerous tissues." (PMID 34659555, 2021). "In our study, it was found that PRR11 is highly expressed in osteosarcoma tissue and is related to tumor size, Enneking stage, and lymph node metastasis." (PMID 34659555, 2021). "The survival time of osteosarcoma patients with positive expression of PRR11 protein was significantly lower than that of patients with negative expression of PRR11 (P=0.025)." (PMID 34659555, 2021). "Our study found that after PRR11 was down-regulated, the invasion and migration ability of osteosarcoma cells U2OS was significantly reduced." (PMID 34659555, 2021). "In summary, in this study, we tested the expression of PRR11 in osteosarcoma tissues and osteosarcoma cell lines." (PMID 34659555, 2021). "Down-regulating the expression of PRR11 can inhibit the proliferation, migration and invasion of osteosarcoma cells and promote cell apoptosis." (PMID 34659555, 2021). "Above all, PRR11 might be an independent and reliable biomarker and therapeutic target for osteosarcoma patients." (PMID 36551227, 2022). "It is proved that PRR11 is highly expressed in osteosarcoma tissues and osteosarcoma cells, and the expression level of PRR11 is significantly correlated with the clinicopathological characteristics and prognosis of patients with osteosarcoma." (PMID 34659555, 2021). "These research data indicate that PRR11 may be involved in the occurrence and development of osteosarcoma as a proto-oncogene, and PRR11 may become a potential indicator and therapeutic target for evaluating the prognosis of osteosarcoma." (PMID 34659555, 2021). "Thus, PRR11 protein expression was significantly lower in the paracancerous tissues compared to osteosarcoma tissues (χ2 = 27.193, P=0.001)." (PMID 34659555, 2021). "However, the up-regulation mechanism of PRR11 in osteosarcoma and the molecular mechanism of how to regulate the expression of Wnt pathway and downstream proteins need to be further explored in future research." (PMID 34659555, 2021). "In our study, we found that PRR11 is highly expressed in osteosarcoma cells." (PMID 34659555, 2021). "Therefore, we speculate that down-regulation of PRR11 may affect the migration and invasion of osteosarcoma by inhibiting the Wnt /β-catenin signaling pathway and then affecting EMT." (PMID 34659555, 2021). "However, the mechanism of PRR11 in osteosarcoma is still unclear." (PMID 34659555, 2021).
osteosarcoma (continued). "Therefore, PRR11 may be used as an oncogene to promote the occurrence and development of osteosarcoma, and is a potential prognostic indicator and therapeutic target in osteosarcoma." (PMID 34659555, 2021). "Plot the survival curve of patients with osteosarcoma from 1 to 24 months of PRR11 positive and negative patients." (PMID 34659555, 2021).